BNIP3L (BCL2 interacting protein 3 like)
Description:
Induces apoptosis. Interacts with viral and cellular anti-apoptosis proteins. Can overcome the suppressors BCL-2 and BCL-XL, although high levels of BCL-XL expression will inhibit apoptosis. Inhibits apoptosis induced by BNIP3. Involved in mitochondrial quality control via its interaction with SPATA18/MIEAP: in response to mitochondrial damage, participates in mitochondrial protein catabolic process (also named MALM) leading to the degradation of damaged proteins inside mitochondria. The physical interaction of SPATA18/MIEAP, BNIP3 and BNIP3L/NIX at the mitochondrial outer membrane regulates the opening of a pore in the mitochondrial double membrane in order to mediate the translocation of lysosomal proteins from the cytoplasm to the mitochondrial matrix. May function as a tumor suppressor.
Synonyms: NIP3L; BNIP3A; NIX
Tractability: Antibody: UniProt predicts a signal peptide or a membrane-spanning region. PROTAC: ubiquitination databases record sites on it; its protein half-life has been measured.
Gene: Protein-coding gene on chromosome 8 (26,383,037 to 26,505,636, forward strand). Ensembl gene ENSG00000104765.
Subcellular location: Nucleus envelope; Endoplasmic reticulum; Mitochondrion outer membrane; Membrane
Subcellular location (Human Protein Atlas): Mitochondria; Nuclear speckles
Gene Ontology:
Molecular function: identical protein binding; lamin binding; protein binding; protein homodimerization activity
Biological process: cellular response to hypoxia; defense response to virus; mitochondrial protein catabolic process; negative regulation of apoptotic process; negative regulation of programmed cell death; positive regulation of apoptotic process; positive regulation of macroautophagy; mitochondrial fragmentation involved in apoptotic process; negative regulation of mitochondrial membrane potential; positive regulation of mitochondrial membrane permeability; regulation of establishment of protein localization to mitochondrion; regulation of mitophagy
Cellular component: endoplasmic reticulum; mitochondrial outer membrane; mitochondrion; nuclear envelope; nuclear speck; membrane; nucleus; mitochondrial envelope
Genetic constraint (gnomAD): Loss-of-function variants: 10 observed, 25.74 expected, observed/expected ratio (o/e) 0.39, 90% interval 0.24 to 0.66. The upper end of that interval is the gene's LOEUF score, 0.66, which puts it in group 2 of 6, group 1 being the genes least tolerant of losing a copy. Missense variants: 215 observed, 281.18 expected, observed/expected ratio (o/e) 0.76, 90% interval 0.68 to 0.86. Synonymous variants: 113 observed, 104.95 expected, observed/expected ratio (o/e) 1.08, 90% interval 0.92 to 1.26.
Homologues: Orthologues: chimpanzee BNIP3L (100% identical), pig BNIP3L (97% identical), rabbit BNIP3L (97% identical), mouse Bnip3l (97% identical), dog PPP2R2A (96% identical), guinea pig BNIP3L (94% identical), macaque BNIP3L (93% identical), rat Bnip3l (90% identical), tropical clawed frog bnip3l (74% identical), zebrafish bnip3la (64% identical), zebrafish bnip3lb (60% identical), Drosophila melanogaster BNIP3 (25% identical), and 1 more. Paralogues in human: BNIP3 (55% identical).
Diseases named in the same sentence as BNIP3L in open-access papers:
BNIP3L is named in the same sentence as 112 diseases in open-access papers, as found by Europe PMC text mining. Sharing a sentence is not in itself a finding about the gene and the disease. The quoted sentences say what the papers report.
breast carcinoma (17 papers, 2003 to 2026). "This idea was further supported by a transcriptome analysis indicating BNIP3L upregulation is closely linked with TNF-α resistance in breast cancer cells." (PMID 34930907, 2021). "To determine if this quiescent state of breast cancer stem cells was linked to activation of autophagy pathway, we assessed the expression of three autophagy related proteins: BNIP3L, BECLIN1, and LC3B." (PMID 28445132, 2017). "Moreover, the ITGB4 protein derived from breast cancer exosomes has been shown to upregulate BNIP3L expression in cancer-associated fibroblasts (CAFs), thereby inducing BNIP3L-dependent mitophagy in CAFs and providing energy metabolites for breast cancer cells." (PMID 39472438, 2024). "In order to determine whether BNIP3L functions as a tumour suppressor gene in breast and/or ovarian cancer, we have analysed its expression in ovarian and breast cancer cell lines and screened all exons for mutations in a panel of primary ovarian and breast cancers." (PMID 12610513, 2003). "A previous study assessed the RNA level of BNIP3L and revealed that the expression of BNIP3L in breast cancer cells was similar to that in normal breast epithelial cells." (PMID 39472438, 2024). "Specifically, it was shown that RL2 treatment caused an upregulation of PINK1, BNIP3, and BNIP3L/NIX and the conversion of LC3 to LC3 II in breast cancer cells." (PMID 38132099, 2023). "In solid tumors (cell lines), breast cancer, glioblastoma, and pancreatic cancer, BNIP3L exacerbate cancer progression." (PMID 34930907, 2021). "In breast cancer cell lines, the blockade of EGFR by antibodies or small-molecule inhibitors induces nuclear translocation of FOXO3a and promotes the expression of BNIP3L gene, which consequently results in apoptotic death of breast cancer cells." (PMID 30045773, 2018). "The other region found altered in cancers of the reproductive system, 8p21.2 harbours the BNIP3L gene and has been identified as a tumor suppressor gene in breast cancer, ovarian cancer, and prostate cancer." (PMID 27876019, 2016). "Both Bnip3 and Bnip3L/Nix mRNA levels are higher in breast cancer tissue than in normal tissue, and correlated with high-grade status and was associated with more invasive cases." (PMID 22984526, 2012). "Quantification of BNIP3L expression showed little variation in the 13 breast cancer cell lines when compared with two immortalised normal breast epithelial cell lines." (PMID 12610513, 2003). "BNIP3L expression was also examined by Northern blotting in a subset of eight of the breast cancer cell lines." (PMID 12610513, 2003). "However, in breast tissue samples, researchers have shown that the level of BNIP3L is greater in primary breast cancers than in normal tissues." (PMID 39472438, 2024). "Three genes, TRADD, BNIP3L, and CASP9, increase in both cell lines with loss of Sin3A, demonstrating that Sin3A possesses some overlapping gene regulation between breast cancer cell lines, as may be expected." (PMID 20920219, 2010). "ITGB4-overexpressing triple negative breast cancer cells provided CAFs with ITGB4 proteins via exosomes, which induced BNIP3L-dependent mitophagy and lactate production, and then promoted the proliferation, EMT and invasion of breast cancer cells." (PMID 38825680, 2024). "To understand the role of autophagy in chemoresistance of breast cancer stem cells, we invalidated BECN1 or BNIP3L expression in XBC4 spheres." (PMID 28445132, 2017). "In addition, another study revealed that BNIP3L is also transcriptionally activated by FOXO3A and sensitizes breast cancer cells to chemotherapy-induced apoptosis." (PMID 39472438, 2024). "BNIP3L, which has sequence homology to pro-apoptotic proteins and the ability to suppress colony formation in soft agar, is located at 8p21, within a region of ovarian cancer LOH, breast cancer LOH and prostate cancer metastasis suppression." (PMID 12610513, 2003).
breast carcinoma (continued). "Interestingly, another study involving IHC analysis of human breast tissues revealed that BNIP3L is abundantly expressed in the stroma of breast cancers but is largely absent from tumor cells." (PMID 39472438, 2024). "The absence of mutations in BNIP3L in breast and ovarian tumours, and the lack of significant downregulation of the gene in either tumour type, suggests that BNIP3L is not the target of 8p LOH in ovarian and breast tumours, despite its location in the SROs of LOH in ovarian cancer and breast cancer." (PMID 12610513, 2003). "In patients with breast cancer brain metastases and uveal melanoma, BNIP3 but not BNIP3L may serve as a putative biomarker." (PMID 34930907, 2021).
pancreatic cancer (11 papers, 2015 to 2026). "Previous studies have indicated that hypermethylation of the BNIP3 promoter was found in pancreatic cancer, and the BNIP3L gene was infrequently mutated in a panel of primary breast and ovarian tumors." (PMID 26432836, 2015). "A growing amount of evidence showed that mitochondrial BNIP3L promotes the survival of glioblastoma cells and pancreatic cancer cells." (PMID 34930907, 2021). "KRASmu pancreatic cancer cells can channel their glucose metabolism away from the mitochondria through programmed mitophagy via the mediator BCL2/adenovirus E1B 19-kDa-interacting protein 3-like (BNIP3L/NIX)." (PMID 37298264, 2023). "Furthermore, BNIP3L-mediated mitophagy might function as a tumor promoter with the evidence that Bnip3l depletion significantly delays the progression of pancreatic cancer and improves the survival in a murine model of pancreatic ductal adenocarcinoma." (PMID 37481562, 2023). "On the other hand, suppression of BNIP3L/NIX results in maintenance of mitochondrial functionality and decreases tumor growth in a pancreatic cancer model, thus showing its oncogenic feature." (PMID 36831455, 2023). "Among them, the mRNA levels of ADM, C4orf3, ERO1L, FUT11, BNIP3L, NDRG1, KCTD11, SLC2A1, and P4HA1 were increased in pancreatic cancer tissues compared to adjacent pancreatic tissues from TCGA and GTEx database." (PMID 34221996, 2021).
Cerebral ischemia (10 papers, 2018 to 2025). Restriction of arterial blood supply to the brain associated with insufficient oxygenation to support the metabolic requirements of the tissue. "Current evidence indicates BNIP3L is involved in acute brain injury disorder including cerebral ischemia, intracerebral hemorrhage (ICH), and traumatic brain injury, while most evidence indicates a proapoptotic role of BNIP3L." (PMID 34930907, 2021). "Our previous work revealed a neuroprotective role of mitophagy in acute brain ischemia in Bnip3l knockout mice." (PMID 34930907, 2021). "Additionally, recent research showed that brain damage was more serious in BNIP3L −/− mice, while more neurons survived after BNIP3L up-regulation in a cerebral ischemia injury." (PMID 40004139, 2025). "Enhanced binding of BNIP3L with LC3 was observed in a delayed manner (72 h) after acute brain ischemia, suggesting excessive mitophagy may be correlated with delayed neuronal death." (PMID 34930907, 2021). "Knockout of the mitophagy-related gene Bnip3L could aggravate cerebral ischemia/reperfusion injury, and overexpression of this gene could rescue." (PMID 33424757, 2020). "However, cerebral ischemia-induced mitophagy at the later stage may depend on the BNIP3L/Nix pathway." (PMID 37856037, 2024). "Previous studies have found that HIF 1a and BNIP3L signal pathways play an important role in the pathogenesis of brain diseases such as cerebral ischemia/reperfusion, cerebral hemorrhage, memory ischemia, glioma and Alzheimer’s disease.The expression levels of HIF-1α and BNIP3L are increased." (PMID 36569834, 2022). "Nevertheless, the contribution of BNIP3L-mediated mitophagy to brain ischemia was not determined by silencing or deleting the Bnip3l gene in animal cells." (PMID 34930907, 2021). "The mitophagy receptors BNIP3L/Nix and FUNDC1 are both mitochondrial outer membrane proteins containing the LC3 interaction region (LIR) that have been shown to mediate hypoxia-induced mitophagy and play important roles in mitophagy-induced by cerebral ischemia." (PMID 37856037, 2024). "Additionally, this study found that only high expression of wild-type BNIP3L could reverse mitochondrial autophagy and reduce ischemic cerebral infarction volume after cerebral ischemia, whereas high expression monomer mutant BNIP3L could not have such effect." (PMID 34335233, 2021).
glioblastoma (9 papers, 2012 to 2026). The most malignant astrocytic tumor (WHO grade IV). "As for drug resistance, the BNIP3L (BCL2/adenovirus E1B 19 kDa interacting protein 3-like)-mediated mitophagy protects glioblastoma from chemotherapy-induced ROS." (PMID 40006565, 2025). "Mitophagy controlled by BNIP3L pathways protects glioblastoma cells from lack of oxygen." (PMID 38334464, 2024).
Parkinson disease (9 papers, 2017 to 2026). A progressive degenerative disorder of the central nervous system characterized by loss of dopamine producing neurons in the substantia nigra and the presence of Lewy bodies in the substantia nigra and locus coeruleus. "In cells derived from patients suffering from Parkinson’s disease (PD), BNIP3L seemingly compensates for the loss-of-function mutation of PRKN/PARK2 and restores mitophagy." (PMID 34930907, 2021). "Unlike the case of PRKN/PARK2 and Parkinson’s disease, there is a paucity of data supporting the association between BNIP3L mutations and specific diseases." (PMID 34930907, 2021). "Accordingly, an MPTP-induced parkinsonism model BNIP3L was downregulated, but this could be reversed through neuroprotectant rescuing dopamine neuron death." (PMID 34930907, 2021). "Overexpression of BNIP3 improved ATP production in Parkinson's disease 105, and BNIP3/BNIP3L-mediated mitophagy protected against brain ischemic injury 106,107." (PMID 39247814, 2024). "In the case of neurodegenerative diseases such as Parkinson’s and ALS, BNIP3L accelerated disease progression." (PMID 34930907, 2021).
ischemic stroke (8 papers, 2020 to 2023). A stroke disorder caused by obstruction of blood flow to the brain, due to thrombotic (local blood clot formation) or embolic (due to a blood clot or other material traveling from another site) event. "Blocking BNIP3L loss with the proteasomal inhibitor drug carfilzomib restored mitophagy and attenuated ischemic stroke." (PMID 34930907, 2021). "We demonstrated BNIP3L is required for ischemia-reperfusion-induced neuronal mitophagy and BNIP3L-mediated mitophagy offers protection against ischemic stroke by reinforcing clearance of damaged mitochondria." (PMID 34930907, 2021). "Additionally, Nix/BNIP3L has now been shown to induce mitophagy in several different type of cells, such as in neurons during ischemic stroke or cerebral ischemia." (PMID 35011599, 2021). "In ischemic stroke, mitophagy could be predominantly mediated by the PINK1/Parkin pathway, Bcl-2/E1B-19 KD-interacting protein 3 (BNIP3), NIP3-like protein X (NIX, also known as BNIP3L), and FUN14 domain containing 1 (FUNDC1)." (PMID 37033646, 2023). "Even after many similarities, the NIX/BNIP3L could not fully compensate for BNIP3 depletion to trigger mitophagy and cell death in response to ischemic stroke." (PMID 35011599, 2021). "Although BNIP3 and NIX/BNIP3L share high degree of sequence homology, elevated NIX/BNIP3L levels could not compensate BNIP3 depletion to trigger mitophagy and cell death in response to ischemic stroke." (PMID 33537304, 2020).
anemia (6 papers, 2012 to 2023). A reduction in the number of red blood cells, the amount of hemoglobin, and/or the volume of packed red blood cells. "Functionally, the activation of BNIP3L-dependent mitophagy is essential for the programmed mitochondrial elimination during erythroid maturation, and BNIP3L-depleted mice show anemia." (PMID 33262988, 2020). "Consequently, mutant reticulocytes are exposed to increased levels of ROS and die, and Nix/Bnip3L knockout mice suffer severe anemia." (PMID 22666256, 2012).
cardiomyopathy (6 papers, 2020 to 2025). A disease of the heart muscle or myocardium proper. "Evidence indicates increased BNIP3L promotes cardiomyocyte apoptosis and causes cardiomyopathy with LV dilation and represses systolic function, whereas reduced BNIP3L protects against apoptotic cardiomyopathy." (PMID 32292354, 2020). "Moreover, cardiac overexpression of BNIP3L/NIX causes a lethal cardiomyopathy with high level of apoptosis and adulthood overexpression of BNIP3L/NIX aggravates cardiac dysfunction post-MI." (PMID 35053316, 2022). "BCL2/adenovirus E1B 19 kDa protein-interacting protein 3-like (BNIP3L) activates the ER and mitochondrial cell death pathways and induces cardiomyopathy." (PMID 39457090, 2024). "The subfamily of pro-apoptotic BCL-2 homology (BH) BH3-only proteins, BCL2/adenovirus E1B 19 kDa protein-interacting protein 3 (BNIP3) and its homologue BNIP3-like (BNIP3L or Nix), also induce apoptosis and the forced expression of these genes is sufficient to induce cardiomyopathy in murine models." (PMID 38391966, 2024). "To investigate whether EPAS1, BNIP3L, and SOD2 induction is a common feature of cardiomyopathy, we also assessed the levels in additional patient hearts with mutations in PKP2 and phospholamban (PLN), associated with ACM and DCM." (PMID 40034852, 2025).
cognitive deficits (6 papers, 2022 to 2025). "In addition, administration of echinomycin rescues cognitive deficits, ameliorates HIF-1α and BNIP3L-mediated neuronal pyroptosis and damaged mitochondrial structures, and decreases the expression of TNF-α and IL-6 in the hippocampus." (PMID 36569834, 2022). "Our results show that CLP-induced hippocampus-dependent cognitive deficits were accompanied with increased HIF 1a and decreased BNIP3L, increased protein levels of TNF-α, IL-6, and IL-β, and damage to mitochondrial structures and neuronal apoptosis in the hippocampus." (PMID 36569834, 2022). "However, because we did not perform knockout experiments for BNIP3L in APP23/PS45 mice, there is insufficient evidence to confirm that BNIP3L-mediated mitophagy directly attenuates cognitive deficits and amyloidosis, with further in vivo studies required." (PMID 39030577, 2024).
hepatocellular carcinoma (6 papers, 2020 to 2026). A malignant tumor that arises from hepatocytes. "In contrast, studies conducted in hepatocellular carcinoma revealed that hepatitis B virus induces BNIP3L-dependent mitophagy that upregulates glycolytic metabolism to increase HCC cell growth." (PMID 34282749, 2021). "BNIP3L is a new prognostic biomarker for melanoma patients and is related to the development and metastasis of hepatocellular carcinoma (HCC) and colon cancer." (PMID 33613623, 2020).
ischemia (6 papers, 2018 to 2025). A hypoperfusion of the BLOOD through an organ or tissue caused by a PATHOLOGIC CONSTRICTION or obstruction of its BLOOD VESSELS, or an absence of BLOOD CIRCULATION. "Recent studies have shown that the re-expression of BNIP3L in mouse cortex and striatum transfected with recombinant adeno-associated virus can reverse the loss of BNIP3L after ischemia and promote mitochondrial autophagy." (PMID 34335233, 2021). "It was suggested that only the protein level of BNIP3L/NIX decreased with the prolonged duration of ischemia time." (PMID 34335233, 2021). "First, BNIP3L/NIX phosphorylation at Ser81 seems to be needed for the induction of mitophagy under ischemia-induced conditions although the responsible kinases still remain uncharacterized." (PMID 30250843, 2018). "It was shown that knockdown of BNIP3L/Nix in differentiating cardiac progenitor cells increased FUNDC1 transcripts, and vice versa, in an adult mouse model of ischemia." (PMID 41369393, 2025). "It is well described that BNIP3 or BNIP3L/NIX activation induces either autophagy or apoptosis depending to the stress conditions and expression of these proteins increases during hypoxia, cardiac hypertrophy or ischemia." (PMID 35053316, 2022).